BRAF (B-Raf proto-oncogene, serine/threonine kinase)
Diseases named in the same sentence as BRAF in open-access papers (continued):
Sharing a sentence is not in itself a finding about the gene and the disease.
lung adenocarcinoma (237 papers, 2007 to 2026). A carcinoma that arises from the lung and is characterized by the presence of malignant glandular epithelial cells. "Here, we describe the first reported case of metastatic BRAF V600E-mutated lung adenocarcinoma that responded to dabrafenib and trametinib, and subsequently developed treatment-associated HLH-like hyperinflammatory syndrome." (PMID 42125703, 2026). "Dabrafenib and trametinib are highly efficacious therapies in patients with BRAF V600E-mutated lung adenocarcinoma (LUAD), but they are occasionally associated with the development of hemophagocytic lymphohistiocytosis (HLH)." (PMID 42125703, 2026). "The management of lung adenocarcinoma with brain metastases (BMs) is particularly challenging when BRAF-V600E mutations emerge as a resistance mechanism to EGFR tyrosine kinase inhibitors." (PMID 41727651, 2026). "Accordingly, the lesion was diagnosed as synchronous thyroid metastasis of lung adenocarcinoma with a BRAF V600E mutation." (PMID 39980562, 2025). "Initial studies using RT-PCR targeting exons 11 and 15 alongside High-Resolution Melting Analysis (HRMA) identified BRAF mutations in approximately 5% of lung adenocarcinomas, with about 58% classified as V600E mutations." (PMID 40332392, 2025). "In this study, a patient with inoperable stage IIIA lung adenocarcinoma and a BRAF V600E mutation achieved a partial response (PR) following neoadjuvant targeted therapy." (PMID 41480531, 2025). "The second patient presented is an 84-year-old male with stage 4 lung adenocarcinoma harboring a BRAF Class II, G469S mutation." (PMID 41282105, 2025). "Taken together, we conclude that the BRAF mutation status lacks prognostic significance in stage I lung adenocarcinoma patients." (PMID 38362771, 2024). "In a lung adenocarcinoma patient‐derived xenograft model and a cell line derived from the xenograft, BRAF G469V was the only known oncogenic mutation, and knockdown of BRAF and not EGFR killed the xenograft‐derived cell line." (PMID 38770647, 2024). "Previous studies have demonstrated that the increased expression of YAP1 or its analog TAZ significantly diminishes the sensitivity of the lung adenocarcinoma cell line carrying the BRAF V600E mutation (HCC364) to vemurafenib and trametinib." (PMID 38499647, 2024). "We report a case of a lung adenocarcinoma patient with a rare BRAF mutation who benefited from the combination therapy of dabrafenib + trametinib." (PMID 38538919, 2024). "This study aimed to evaluate the prognostic significance of BRAF mutations in patients with pathological stage I lung adenocarcinoma." (PMID 38362771, 2024). "We present a patient with lung adenocarcinoma showing high PD-L1 expression and BRAF V600E mutation, who achieved a remarkable long-term response to the combination therapy of dabrafenib and trametinib (DT treatment) after disease progression on immunotherapy." (PMID 38429896, 2024). "The data of the prognostic role of V‐Raf murine sarcoma viral oncogene homolog B1 (BRAF) mutations in early‐stage lung adenocarcinoma (LUAD) patients is scarce." (PMID 38362771, 2024). "The estimated BRAF mutation rate in lung adenocarcinoma was 5.6%, which is in line with previous studies." (PMID 38362771, 2024). "The BRAF V600E mutation is detected in ~1–2% of patients diagnosed with lung adenocarcinoma, and targeted therapies against BRAF have shown promising results in treating these patients." (PMID 38499647, 2024). "BRAF serine-threonine kinase p.V600E mutations are present in approximately 1% to 2% of lung adenocarcinomas." (PMID 38124787, 2023). "BRAF mutations are seldom detected in lung tumors, with frequencies varying from 2.2% to 4.9% in lung adenocarcinoma and reaching up to 5.4% in NSCLC." (PMID 37999148, 2023). "Even in lung adenocarcinoma BRAF mutations play a clinical role, although limited by the low frequency." (PMID 36758042, 2023).
lung adenocarcinoma (continued). "In B-Raf proto-oncogene(BRAF)-driven lung adenocarcinoma cells, loss of CTR1 leads to a decrease in copper ion concentration that is directly associated with reduced function of MEK1/2 and ULK1/2, key kinases in both signaling pathways." (PMID 36882769, 2023). "Apart from EGFR and KRAS, the proto-oncogene B-Raf (BRAF) gene that encodes a serine/threonine kinase was identified in 3% (18/687) of western patients with lung adenocarcinomas but only in 0.5% (25/5,125) of Asian patients." (PMID 36059824, 2022). "For patients with driver mutations, such as EGFR (10% of NSCLC cases) and BRAF (0.5–4.9% of lung adenocarcinomas), and rearrangements in ROS1 (1–2% of lung adenocarcinomas) and ALK (3–7% of lung adenocarcinomas) gene-targeted therapy can be used." (PMID 35216378, 2022). "A 72-year-old male patient with advanced lung adenocarcinoma harboring a BRAF mutation had received treatment with a BRAF inhibitor and a MEK inhibitor." (PMID 35242521, 2022). "CT-based radiomics has predicted the mutation status in patients with CRC and in lung adenocarcinoma patients for KRAS/BRAF and EGFR, respectively." (PMID 36612061, 2022). "We corroborated the BRAF V600E mutation and high PD-L1 expression and supported the molecular features of lung adenocarcinoma." (PMID 36003386, 2022). "Here, we report a case of BRAF mutation-positive lung adenocarcinoma with an atypical clinical course and long-term survival." (PMID 35464513, 2022). "We describe the case of a 63-year-old man with a stage cIVA ALK-rearranged lung adenocarcinoma who developed a BRAF A598-T599insV mutation as a potential resistance mechanism to alectinib, a second-generation ALK TKI." (PMID 36419902, 2022). "Herein, we report a case of lung adenocarcinoma harboring a complex ALK fusion that coexisted with a BRAF mutation, as tested by DNA-NGS prior to treatment." (PMID 36221356, 2022). "An 86‐year‐old male patient, who had been diagnosed with lung adenocarcinoma with BRAF V600E mutation, received dabrafenib and trametinib combination chemotherapy." (PMID 33215864, 2021). "The BRAF V600E mutation in lung adenocarcinoma (LUAD) or other amino acid changes in BRAF showed relatively low MSCs." (PMID 34424899, 2021). "An 86‐year‐old male patient, who had been diagnosed with lung adenocarcinoma with the BRAF V600E mutation, received dabrafenib and trametinib combination chemotherapy." (PMID 33215864, 2021). "In summary, our data uncover basic principles of drug-induced evolutionary paths underlying BRAF-driven resistance in patients with lung adenocarcinoma." (PMID 34921211, 2021). "One patient had a sustained CR for >1 year; this patient had lung adenocarcinoma and received vemurafenib for a BRAF mutation." (PMID 34540658, 2021). "We report a case of BRAF V600E-mutated lung adenocarcinoma, which presented with respiratory distress due to deterioration of advanced cancer." (PMID 34484797, 2021). "Within the present study, we aimed for a comprehensive and translational approach to systematically characterize the role of co-occurring EGFR/BRAF mutations in patients with advanced lung adenocarcinoma." (PMID 34921211, 2021). "For example, KRAS mutation was found in 30 % of lung adenocarcinoma patients, while BRAF mutation was less frequent." (PMID 33593390, 2021). "Noteworthy, in one study, dabrafenib was successfully adopted when a BRAF exon 15 p.V600E-mutated lung adenocarcinoma patient became resistant to vemurafenib." (PMID 33260892, 2020). "By tracking the evolution of lung adenocarcinomas, most BRAF, EGFR, and KRAS activating mutations are trunk drivers." (PMID 32333643, 2020). "The two main types of BRAF mutations, V600E and non-V600E, are associated with different clinicopathological features of lung adenocarcinoma and exhibit different therapeutic response to BRAF-targeted targeted agents." (PMID 31882684, 2019).
lung adenocarcinoma (continued). "BRAF mutations occurred in about 2–4% of lung adenocarcinoma, and approximately 50% of them were BRAF V600E mutations." (PMID 31023335, 2019). "Up to 8% of lung adenocarcinomas harboured BRAF mutations in recent studies (including Italian cohorts), most of them being the V600E mutation, which was the only BRAF alteration detected in our cohort in 3.2% of the cases examined." (PMID 31711449, 2019). "For example, in lung adenocarcinoma, it is estimated that approximately half of the mutations in BRAF are non-V60020." (PMID 31723142, 2019). "These authors demonstrated that the expression of an endogenous kinase-inactive BRAF mutant triggered the development of lung adenocarcinoma in mice, indicating that BRAF-inactivating mutations initiate lung oncogenesis." (PMID 29690599, 2018). "Of note, it was reported in a case study, that a female patient with non-V600 BRAF (G469R) mutated lung adenocarcinoma showed dramatic response to sorafenib treatment." (PMID 29739364, 2018). "The most likely interpretation of these observations is that the invasive clone rarely develops from a lesion with a BRAF mutation, in line with the observation that the frequency of BRAF mutations in invasive lung adenocarcinomas is low (2−3%)." (PMID 30060526, 2018). "Treatment responses induced by BRAF inhibitors in BRAF V600E-mutated lung adenocarcinoma have also been reported." (PMID 29879227, 2018). "A search of cell lines from lung adenocarcinoma with BRAF mutation can be easily accomplished using this Boolean logic search." (PMID 29726944, 2018). "For the first time, we evaluated the possibility of CastPCR detecting EGFR and BRAF mutations in cfDNA of plasma from 107 lung adenocarcinoma patients." (PMID 28572536, 2017). "The mutation BRAFV600E can be activated by certain drugs notably for patients with different solid tumors and BRAF mutations are present in 2–3% of lung adenocarcinomas." (PMID 29125548, 2017). "For the first time, we evaluated the feasibility of CastPCR detecting EGFR and BRAF mutations in plasma cfDNA of a cohort lung adenocarcinoma patients." (PMID 28572536, 2017). "And we firstly found complex BRAF mutations in plasma cfDNA of lung adenocarcinoma: two with p.G469A + p.D594G, one with p.D594G + p.V600E and one with p.G469A + p.D594G + p.V600E." (PMID 28572536, 2017). "We performed BRAF mutation detection in 107 pairs of lung adenocarcinoma plasma cfDNA and matched FFPE DNA samples." (PMID 28572536, 2017). "Conversely, another case report of a patient with lung adenocarcinoma harboring BRAF G469R mutation, showed a strong and rapid response to sorafenib for up to 6 months." (PMID 27388325, 2016). "Point mutation of the BRAF gene is a genetic event that occurs in a subset of lung adenocarcinoma cases." (PMID 25621040, 2015). "Increased BRAF gene copy number was identified in three lung adenocarcinoma patients (10.3%), all of which exhibited the V600E mutation." (PMID 25621040, 2015). "In lung adenocarcinoma BRAF mutations are found in 1%–5%, half of them harboring the classical V600E mutation." (PMID 26018876, 2015). "One to two percent of lung adenocarcinomas have a BRAF mutation, which is an oncogenic driver." (PMID 40729346, 2025). "Thyroid metastasis of BRAF V600E-mutated lung adenocarcinomas is rare." (PMID 39980562, 2025). "A bronchoscopic biopsy confirmed primary lung adenocarcinoma harboring the BRAF V600E mutation." (PMID 39759653, 2024). "In some patients, a BRAF-V600E-mutated lung adenocarcinoma coexisted with BRAF-mutated HCL." (PMID 39272912, 2024). "Theis may suggest that lung adenocarcinoma with micropapillary should be first considered to conduct BRAF mutation testing." (PMID 37374289, 2023). "BRAF mutations affect from 2.2% to 4.9% of lung adenocarcinomas." (PMID 37999148, 2023). "Interestingly, one patient carried BRAF V600E mutation, which occurs in only 1–4% of lung adenocarcinoma." (PMID 36672660, 2023).
lung adenocarcinoma (continued). "The clinical impact of BRAF mutational subtypes on lung adenocarcinoma remains to be defined." (PMID 36230688, 2022). "BRAF mutation rate is higher in patients with advanced lung adenocarcinoma." (PMID 32729257, 2020). "Therefore, our results support that the class II and class III BRAF alterations are indeed driver mutations in lung adenocarcinoma." (PMID 31533235, 2019). "Additionally, CastPCR technology was firstly employed to detect BRAF mutations in plasma specimens of lung adenocarcinoma and their matched FFPE samples." (PMID 28572536, 2017). "BRAF mutations in lung adenocarcinoma would be of interest as these mutations may be associated with increased sensitivity to agents directly targeting BRAF or BRAF-mediated downstream signaling pathways." (PMID 25621040, 2015). "Ongoing trials in BRAF mutated lung adenocarcinoma investigate BRAF-, MEK- and AKT-inhibitors." (PMID 26018876, 2015). "DNA sequencing confirmed the presence of KRAS mutations, one of the most common driver mutations in lung adenocarcinoma, in three of the xenograft models and mutations in BRAF and NRAS, two less frequently occurring mutations associated with NSCLC, in two of the models." (PMID 22992329, 2012). "BRAF mutations, for instance, are found in approximately 3% of adenocarcinoma of the lung." (PMID 25562798, 2012). "The set of novel isoform-switching genes included the proto-oncogene BRAF (BRAF-204, −0.88 log fold-change, adjusted P-value 1.183 × 10−5; BRAF-206, 1.13 log fold-change, adjusted P-value 1.085 × 10−2) for which cancer-causing mutations in lung adenocarcinoma have been previously identified." (PMID 39498433, 2024). "Using targeted next-generation sequencing (NGS) of 1021 cancer-related genes, we found the emergence of a BRAF V600E mutation in the peripheral blood of a patient with ALK-rearranged lung adenocarcinoma after treatment progression on ALK-TKIs, which may explain the resistance." (PMID 33663128, 2021). "More recently, analysis of circulating tumor cell-free DNA from lung adenocarcinoma patients indicated an even higher prevalence, near 9%; however, only 2% of these were BRAF V600E." (PMID 40332392, 2025). "For instance, a male patient with lung adenocarcinoma underwent genetic testing after osimertinib treatment failure, which revealed co-mutations of EGFR T790M/19del and BRAF V600E." (PMID 39135785, 2024). "The patient was finally diagnosed as left lung adenocarcinoma with left pleural and pericardial metastases (cT3N0M1a, stage IVA, BRAF ex15 p.T599dup mutation positive)." (PMID 38538919, 2024). "We report a case of 70‐year‐old woman with BRAF V600_W604 deletion–insertion R‐positive stage IVA lung adenocarcinoma, who was successfully treated with dabrafenib plus trametinib." (PMID 38766698, 2024). "In this study, genotyping of resected tumor tissue from an elderly female patient diagnosed with lung adenocarcinoma reported the co-mutations of EGFR L858R/G719S and BRAF V600E." (PMID 39135785, 2024). "With BRAF expression, there were 527 lung adenocarcinoma patients and 502 lung squamous cell carcinoma patients." (PMID 37069494, 2023). "The EZH2 gene expression of lung adenocarcinoma was positively correlated with the gene expression of BRAF (r = 0.2633, p < 0.0001) and KRAS (r = 0.31229, p < 0.0011)." (PMID 37069494, 2023). "EGFR, ALK, BRAF, KRAS, ROS1 are the five common genes in lung adenocarcinoma, and EGFR gene mutation is the most common." (PMID 37340599, 2023).
lung adenocarcinoma (continued). "TCN1 is closely related to the molecular targets of lung adenocarcinoma BRAF, HHLA2, and CD274 (PD-L1), especially BRAF and HHLA2." (PMID 35287670, 2022). "BRAF non-Val600 mutations and RUNX1T1 amplifications seem to be unusually prevalent and ALK fusions rare in Finnish lung adenocarcinoma patients." (PMID 35964518, 2022). "Four cases were reported that BRAF fusion was a mechanism of EGFR-TKI acquired resistance in EGFR mutant lung adenocarcinoma." (PMID 35912223, 2022). "We report a case of lung adenocarcinoma harboring a complex EML4-ALK (E13, A5, A20) fusion that coexisted with a BRAF mutation, as tested by DNA-NGS prior to treatment." (PMID 36221356, 2022). "Similar findings were detected in EGFR-mutant lung adenocarcinoma preclinical models and individuals with BRAF V600E lung adenocarcinoma." (PMID 36230484, 2022). "Common driver mutations (EGFR, ALK, BRAF, ERBB2, KRAS, MET, RET, and ROS1) analysis were performed in lung adenocarcinoma tissue samples from two PEAC patients (P08 and P10) using next-generation sequencing." (PMID 35172862, 2022). "This led to the identification of 15 patients with lung adenocarcinoma harboring activating EGFR mutations and co-occurring BRAF mutations." (PMID 34921211, 2021). "Oncogenes were detected in 64% of lung adenocarcinomas, while available information in relation to EGFR, BRAF, KRAS, ALK, ROS1, and MET gene mutations in lung adenocarcinomas are growing steadily." (PMID 34708154, 2021). "Herein, we present a case of PD-L1-overexpressing lung adenocarcinoma that harbors both EML4-ALK gene rearrangement and BRAF mutation." (PMID 34804000, 2021). "To dissect the role of NKX2-1 in mutant BRAF-induced lung adenocarcinoma, we utilized two established mouse strains bearing recombinase-activatable alleles of BrafV600E." (PMID 33821796, 2021). "We present a case of ALK-rearranged lung adenocarcinoma with acquired resistance to ALK inhibition, in which the BRAF V600E mutation is a novel resistance mechanism." (PMID 33663128, 2021). "Some mutations of common driver genes for lung adenocarcinoma also have been identified in BAs, such as EGFR, KRAS and BRAF." (PMID 34663408, 2021). "Our study reports a retrospective analysis on OS rates observed in patients with lung adenocarcinoma harboring somatic mutations either in EGFR and KRAS genes, or in less frequently studied genes, such as BRAF, PIK3CA, NRAS, and HER2 (niche mutations)." (PMID 32082488, 2020). "Intriguingly, it has been seen that driver fusions in lung adenocarcinomas co-occur with SETD2 mutations (16% of cases) in contrast with lung adenocarcinomas with EGFR, KRAS, BRAF and MET mutations, where the frequency of SETD2 mutations is only 2%." (PMID 32516941, 2020). "Here, we present a case of a patient with BRAF V600E positive lung adenocarcinoma who was diagnosed with granulomatosis with polyangiitis (GPA) shortly after initiation of targeted therapy with dabrafenib and trametinib." (PMID 32131760, 2020). "1,760 lung adenocarcinoma patient blood samples were tested for analyzing mutations in EGFR, KRAS, NRAS, PIK3CA, HER2, BRAF and MET in cfDNA." (PMID 31749831, 2019). "For instance, the PC14_PE6_Br2 lung adenocarcinoma cell line, which is BRAF wild type, was also sensitive to β-sitosterol treatment, but to a lesser extent." (PMID 30971321, 2019). "The type IIa BRAF inhibitor PLX7904 and its optimized analogue PLX8394 have been shown to inhibit signaling driven by V600 and non-V600 mutants in lung adenocarcinomas, where 48% of BRAF mutant tumors have non-V600 mutations." (PMID 31398831, 2019). "Following the identification of KRAS and BRAF mutations, epidermal growth factor receptor (EGFR) mutations were discovered in patients with lung adenocarcinoma and were associated with response to EGFR inhibitors." (PMID 31092229, 2019).